SLC5A10 (solute carrier family 5 member 10)
Description:
[Isoform 1]: Electrogenic Na+-coupled sugar symporter that actively transports D-mannose or D-fructose at the plasma membrane, with a Na+ to sugar coupling ratio of 1:1. Transporter activity is driven by a transmembrane Na+ electrochemical gradient set by the Na+/K+ pump. Exclusively recognizes sugar substrates having a pyranose ring with an axial hydroxyl group on carbon 2. Has likely evolved to enable renal reabsorption of D-mannose, an important constituent of oligosaccharide chains of glycoproteins. Contributes to dietary D-fructose reabsorption from glomerular filtrate across the brush border of the kidney. [Isoform 2]: Appears to have no transporter activity.
Synonyms: SGLT5; SGLT-5
Tractability: Small molecule: it belongs to a druggable protein family. Antibody: its Gene Ontology location is reachable by antibodies, with high confidence; UniProt places it where antibodies can reach, with medium confidence; UniProt predicts a signal peptide or a membrane-spanning region.
Gene: Protein-coding gene on chromosome 17 (18,950,345 to 19,022,595, forward strand). Ensembl gene ENSG00000154025.
Subcellular location: Apical cell membrane
Pathways (Reactome):
Transport of small molecules: Cellular hexose transport
Gene Ontology:
Molecular function: fructose:sodium symporter activity; mannose:sodium symporter activity; solute:sodium symporter activity; transmembrane transporter activity
Biological process: hexose transmembrane transport; fructose transmembrane transport; mannose transmembrane transport; sodium ion transmembrane transport; transmembrane transport
Cellular component: extracellular exosome; apical plasma membrane; plasma membrane; membrane
Genetic constraint (gnomAD): Loss-of-function variants: 55 observed, 69.05 expected, observed/expected ratio (o/e) 0.8, 90% interval 0.64 to 1. The upper end of that interval is the gene's LOEUF score, 1, which puts it in group 4 of 6, group 1 being the genes least tolerant of losing a copy. Missense variants: 699 observed, 794.44 expected, observed/expected ratio (o/e) 0.88, 90% interval 0.83 to 0.94. Synonymous variants: 327 observed, 335.01 expected, observed/expected ratio (o/e) 0.98, 90% interval 0.89 to 1.07.
Homologues: Orthologues: chimpanzee SLC5A10 (99% identical), macaque SLC5A10 (98% identical), dog SLC5A10 (92% identical), guinea pig SLC5A10 (89% identical), mouse Slc5a10 (89% identical), rat Slc5a10 (87% identical), pig SLC5A10 (87% identical), rabbit SLC5A10 (85% identical), tropical clawed frog slc5a10 (73% identical), zebrafish slc5a10 (72% identical), Drosophila melanogaster rumpel (19% identical), Drosophila melanogaster CG2187 (19% identical), and 10 more. Paralogues in human: SLC5A9 (62% identical), SLC5A2 (56% identical), SLC5A1 (55% identical), SLC5A11 (52% identical), SLC5A4 (50% identical), SLC5A3 (47% identical), SLC5A6 (22% identical), SLC5A8 (22% identical), SLC5A12 (21% identical), SLC5A5 (21% identical), SLC5A7 (17% identical).
Diseases named in the same sentence as SLC5A10 in open-access papers:
SLC5A10 is named in the same sentence as 18 diseases in open-access papers, as found by Europe PMC text mining. Sharing a sentence is not in itself a finding about the gene and the disease. The quoted sentences say what the papers report.
Hepatic steatosis (4 papers, 2013 to 2025). Steatosis is a term used to denote lipid accumulation within hepatocytes. "Under a high-fat diet, Slc5a10 knockout mice exhibited more severe hepatic steatosis compared to wild-type mice, indicating a previously unrecognized link between renal fructose reabsorption and hepatic lipid metabolism mediated by SGLT5." (PMID 39850557, 2024).
diabetes (3 papers, 2017 to 2022). "Intriguingly, both Slc5a10 and Aldob are involved in fructose metabolism and are upregulated in diabetes." (PMID 35862726, 2022). "The large effect sizes and protein-altering, multiple independent signals suggest SLC5A10 may code for an important transporter of 1,5-AG in the kidney, with a potential nonglucose-related effect on 1,5-AG, impacting its clinical utility as a diabetes biomarker in this subpopulation." (PMID 30976018, 2019).
Hyperglycemia (3 papers, 2019 to 2020). An increased concentration of glucose in the blood. "We observed significant downregulation of Mafa, Ins1, and Ins2 mRNAs, and significant upregulation of Aldob, Slc5a10, Wnt5b, Hk1, and Tnfrsf11b mRNAs, suggesting that the molecular defect results directly from the loss of Cnot3, rather than to hyperglycemia." (PMID 32859966, 2020).
non-small cell lung carcinoma (1 paper, 2023). A group of at least three distinct histological types of lung cancer, including non-small cell squamous cell carcinoma, adenocarcinoma, and large cell carcinoma. "Previous research reported that SLC5A10 rs2257609 C>T affected the prognosis of early-stage non-small-cell lung cancer by influencing the expression of DRG232." (PMID 38021150, 2023).
cancer (2 papers, 2020 to 2023). A tumor composed of atypical neoplastic, often pleomorphic cells that invade other tissues. "Among the 850 hypoxia-related genes, 6 genes (LOC101928143, LOC102723407, MIR1281, PLA2G4B, SLC5A10, and G6PC1) were absent from the TCGA pan-cancer RNA-seq data; thus, 844 genes with RNA expression values were used in the analysis." (PMID 38248716, 2023).
psychiatric disease (1 paper, 2022). "The two CpGs identified in the meta-analysis that were present on both array types were also associated in GS:SFHS and were annotated to genes previously implicated in psychiatric disease and the innate immune system (SKI, SLC5A10)." (PMID 34880450, 2022).
SLC5A10 also shares sentences with these, for which no sentence is quoted: neutropenia (2 papers); atherosclerosis (1); cardiovascular disease (1); cervical adenocarcinoma (1); cervical cancer (1); cervical squamous cell carcinoma (1); Glucose intolerance (1); Hyperinsulinemia (1); Hypertension (1); Insulin resistance (1); liver cancer (1); oligospermia (1).